BRAF (B-Raf proto-oncogene, serine/threonine kinase)
Diseases named in the same sentence as BRAF in open-access papers (continued):
Sharing a sentence is not in itself a finding about the gene and the disease.
glioma (continued). "In order to understand mechanisms of adaptive resistance to BRAFi/MEKi in glioma, we evaluated protein expression in a cohort of human BRAF V600E mutant glioma specimens obtained preceding treatment with BRAFi/MEKi and compared them against tissue obtained at the time of progression." (PMID 40900823, 2025). "This study sought to explore the prevalence of BRAF V600E mutation and CDKN2A deletion in pediatric patients with high-grade glioma (HGG) and aimed to add to the scarce data in the literature about the prognosis of this subset of patients treated with traditional surgery, radiation and chemotherapy." (PMID 40860828, 2025). "Furthermore, successful treatment of gliomas harboring BRAFV600E mutation with BRAF/MEK-inhibitors—dabrafenib plus trametinib—has been reported, with objective response rates of 33% in high-grade gliomas." (PMID 40075591, 2025). "It has also been used to detect complex CNVs such as JAK1-PAK2, JAK1-PVT1, JAK1-MYOCD, JAK1-TIMM21, USP7-TIMM21, and JAK1-Chr22 CNVs in whole blood-derived ovarian cancer samples, EGFR, CDKN2A, and BRAF CNV in glioma tissues, as well as FGFR2 CNV in colorectal and gastric adenocarcinomas." (PMID 40725150, 2025). "This indicates that BRAF/MEK can serve as an important drug target for glioma cells." (PMID 40535548, 2025). "Moreover, BRAF mutant paediatric low-grade glioma cells in vitro secrete microglia-recruiting cytokines." (PMID 39948623, 2025). "A different picture can be seen in pediatric neuro-oncology, where the use of NGS is already recommended in clinical routine as BRAF inhibitors can be used for the treatment of BRAF-mutant higher-grade gliomas, alone or in combination with mitogen-activated protein kinase (MEK) inhibitors." (PMID 40075591, 2025). "To understand whether our BRAF-mutant cell lines were biologically relevant for evaluating resistance in human gliomas, we first sought to clarify the lines’ dependence on oncogenic BRAF V600E versus exogenous growth factors for RAF-ERK signaling." (PMID 40900823, 2025). "Finally, we report new associations between rare germline pathogenic CPG variants and somatic alterations in patients with high-grade glioma, BRAF fusion-positive low-grade gliomas, and medulloblastoma." (PMID 39974082, 2025). "The BRAF V600E mutation, a target for current molecular therapies, has previously been detected in various childhood tumours such as pleomorphic astrocytomas (66.7%), Langerhans cell histiocytosis (LCH) (57%) and low-grade gliomas." (PMID 39671021, 2025). "The 8 low-grade gliomas harbored alterations in BRAF, KRAS, FGFR3, and MN1." (PMID 40980447, 2025). "However, to the best of our knowledge, there are currently no meta-analyses summarizing the published evidence involving the efficacy of dabrafenib and/or trametinib treatment in BRAF V600E mutant glioma patients.." (PMID 39172230, 2024). "Such combinatorial strategies could lead to more effective and comprehensive treatment protocols, ultimately improving prognosis and quality of life for pediatric patients with BRAF-mutant gliomas." (PMID 39654184, 2024). "Because the BRAF fusion is expressed in 70% of PAs, we prospectively collected patients’ glioma samples to comprehensively characterize the unique immune biology of these tumors using NanoString profiling, scRNA-Seq, and sequential immunofluorescence (seqIF) multiplex staining." (PMID 39137048, 2024). "Also, this study statistically supported the advantage of disease response improvement after the combination therapy in BRAF v600-mutant glioma patients, which were shown as a pooled rate of PR (30%), a pooled rate of CR (18%), and a pooled rate of ORR (39%)." (PMID 39172230, 2024). "Therefore, this meta-analysis aimed to explore the effects of dabrafenib combined with trametinib treatment in BRAF V600-Mutant glioma patients by comprehensively analyzing currently available studies." (PMID 39172230, 2024).
glioma (continued). "Based on current literature outcomes, dabrafenib and/or trametinib may lead to the median PFS of 6.10 months and median OS as 22.73 months for BRAF v600-mutant glioma patients, and the safety of monotherapy is better than that of combination therapy." (PMID 39172230, 2024). "Some biological markers suggest that gliomas may have more drug options, such as IDH mutation, EGFR amplification, and BRAF V600E mutations." (PMID 39118481, 2024). "Although we focused on the indication of anti-TIM3 in BRAF fusion PA, which accounts for the majority of pediatric gliomas, this could be further explored in high-grade, BRAF-driven gliomas such as pleomorphic xanthoastrocytoma." (PMID 39137048, 2024). "A case report about recurrent BRAF V600E-mutant adult gliomas found that after a failure of a BRAF inhibitor alone, a BRAF inhibitor combined with a MEK inhibitor could exert a markedly prolonging OS." (PMID 39172230, 2024). "Even though the most recent studies used the combination of BRAFis and MEKis, and some studies suggest that the combination provides better disease control and decreases adverse events, our group felt it was reasonable to use BRAFis as monotherapy for some patients with BRAF V600E mutant gliomas." (PMID 39057171, 2024). "Additionally, TIM3 expression has been correlated with BRAF status in other cancers, suggesting a therapeutic benefit in non-CNS cancers." (PMID 39137048, 2024). "An excellent example in pediatric neuro-oncology is the use of trametinib (MEK inhibitor) and dabrafenib (BRAF inhibitor) in patients with BRAF V600-mutant low-grade glioma, which exhibited a better overall response rate compared to standard chemotherapy regimen." (PMID 38139220, 2023). "First, BRAF alterations co-occur with alterations similar to those observed in other cancers, suggesting they may portend similar functional effects in glioma." (PMID 36854806, 2023). "Interestingly, gliomas with BRAF gains often exhibited focal chromosome 7q gains, suggesting either an advantageous amplification or that BRAF is a passenger amongst other genes promoting glioma progression." (PMID 36854806, 2023). "Finally, CTCs can provide molecular insight into tumor biology and can help direct targetable treatment such as H3K27M in DIPG and BRAF in patients with low-grade gliomas." (PMID 37568669, 2023). "Furthermore, in the presence of cromolyn, K+ channel activity was decreased, leading to lower levels of p-BRAF and diminished glioma cell viability." (PMID 36763212, 2023). "Following these encouraging data, a phase II randomized study comparing first-line combination dabrafenib plus trametinib (D + T) versus traditional chemotherapeutic agents carboplatin plus vincristine (C + V) in BRAF V600–mutant–positive pediatric glioma patients has been undertaken (NCT02684058)." (PMID 37124503, 2023). "This allowed characterization of non-canonical mutations in BRAF present in adult gliomas; improved estimates of relative frequencies and composition of BRAF alteration types; and integrated clinical-genomic analyses to potentially aid in prognostication." (PMID 36854806, 2023). "Considering the infrequent occurrence of BRAF mutations in glioblastoma, there is little clinical data on the efficacy of BRAF inhibitors in glioblastoma specifically, rather, clinical trials may include all types of BRAF V600E-mutant glioma." (PMID 37857607, 2023). "Conversely, BRAF alterations are rarely found in adult gliomas, although activation of the MAPK is seen in 70% of GBM through amplifications or fusions in EGFR/PDGFRA/MET/FGRF1/2/3 genes or mutations in MAPK pathway members particularly NF1, reported in 15% of GBM." (PMID 37124503, 2023). "A phase II trial has evaluated the use of the BRAF inhibitor dabrafenib in combination with the MEK inhibitor trametinib in children and adolescents with relapsed and refractory BRAF-mutated high-grade glioma (NCT02684058)." (PMID 37213274, 2023).
glioma (continued). "BRAF is reportedly the most altered gene in pediatric glioma, including BRAF fusion alterations." (PMID 37280243, 2023). "In terms of molecular therapeutic approaches for gliomas, two therapeutic approaches are already standard of care for patients with gliomas harboring BRAF-V600E alterations and for patients with tuberous sclerosis and subependymal giant cell astrocytoma (SEGA)." (PMID 38275375, 2023). "In this cohort, several important characteristics of BRAF alterations in adult glioma emerge." (PMID 36854806, 2023). "Finally, the infant-type hemispheric glioma category often carries RTK fusions involving the NTRK, ROS1, ALK, and MET genes, while BRAF V600E mutations are observed in 10-15% of pediatric HGGs." (PMID 37213274, 2023). "Recently, the pan-RAF inhibitor tovorafenib (DAY101), provided encouraging response data in pediatric and young adult pretreated patients with recurrent or progressive low-grade glioma or advanced solid tumors harboring a known activating BRAF alteration (NCT04775485)." (PMID 37213274, 2023). "Based on our investigation, we have concluded that KCNMA1 expression is not simply biased toward high grade gliomas, but is linked more specifically to the BRAF mutations that enhance tumor proliferation." (PMID 36763212, 2023). "A subset of gliomas across all ages with Class I BRAF mutations harbored no other alterations, including a subset histologically defined as GBMs." (PMID 36854806, 2023). "Both the PI3K/Akt/mTOR and Ras/BRAF/Mek/Erk protein kinase pathways are also downstream of receptors such as EGFR, one of the most significant signaling pathways clinically implicated in glioma." (PMID 37445633, 2023). "Low-grade gliomas of the midline are more likely to harbor BRAF fusions whereas hemispheric tumors are more likely to have BRAF p.V600E alterations which may inform initial molecular test selection." (PMID 36969278, 2023). "The age at onset for FGFR1MUT DMG is significantly higher (median 14.8 years) and to our knowledge no adults were affected by a H3.3-K27M BRAF-mutated gliomas." (PMID 38066305, 2023). "Gliomas with BRAF gains commonly had concomitant gains in MET, SMO, EZH2, and CDK6 (p < 0.001 each), along with other genes on 7q, which may reflect larger chromosomal duplications." (PMID 36854806, 2023). "Gliomas with distinct BRAF alteration types exhibited varying survival." (PMID 36854806, 2023). "To date, targeted therapy is a promising option for pediatric gliomas harboring BRAF alterations." (PMID 36612052, 2022). "The common BRAF V600E mutation and the KIAA1549-BRAF fusion are present in gliomas." (PMID 34687436, 2022). "In high-grade gliomas, it may become a biomarker of benefit from dabrafenib (BRAF inhibitor) and trametinib (MEK inhibitor) dual-targeted therapy." (PMID 35785151, 2022). "However, targeted therapies are under investigation in low-grade gliomas, such as an upcoming European trial of frontline MEK inhibition or studies of BRAF inhibition in V600E mutated tumours." (PMID 35449451, 2022). "However, trials investigating BRAF/MEK inhibitors in glioma allows the use of IHC and PCR testing especially for identification of BRAFV600E mutation." (PMID 36686797, 2022). "Recently, it was reported that B-Raf (BRAF) is a prognostic marker in glioma." (PMID 36003762, 2022). "To surmount this barrier, we leveraged human induced pluripotent stem cell (hiPSC) engineering to generate low-grade gliomas (LGGs) harboring the two most common pediatric pilocytic astrocytoma-associated molecular alterations, NF1 loss and KIAA1549:BRAF fusion." (PMID 35986378, 2022). "In an open-label, nonrandomized multicohort, ‘basket’ study (VE-BASKET) efficacy and safety of vemurafenib monotherapy was shown in patients with nonmelanoma tumor including 24 BRAF-V600E mutated gliomas." (PMID 35158978, 2022).
glioma (continued). "We underline that spinal astrocytoma molecular features, are still largely under-investigated, and that they could result extremely useful for therapeutic approach (i.e., BRAF–MEK inhibitors for BRAF mutant glioma)." (PMID 35267601, 2022). "In addition to the most common GBM‐related genes, we also found mutations in the BRAF and EGFR genes, previously shown to be involved in glioma progression." (PMID 34875133, 2022). "Certain glioma-associated biomarkers can be assessed by immunohistochemistry, including IDH1 R132H, H3 K27M and H3 G34R/V, loss of nuclear ATRX expression, and BRAF V600E mutation." (PMID 35361262, 2022). "Mutation hotspots such as BRAFV600, IDH1R132, IDH2R172, and IDH2R140 are prime examples where identifying mutational status during surgery could inform more-aggressive resection (BRAF mutant) or less-aggressive resection (IDH1/2 mutant) of gliomas." (PMID 35840782, 2022). "BRAF alterations may also be occasionally seen in diffuse lower-grade gliomas and glioblastoma, especially in the astrocytic lineage (up to 15% in grade II and III astrocytomas and 9% in glioblastomas)." (PMID 34360713, 2021). "We show the ability to detect circulating BRAF V600E in 4/5 patients with known BRAF mutant tumors in our small cohort of patients with metastatic disease, including brain metastasis (n = 3) and primary gliomas (n = 2)." (PMID 33799709, 2021). "Current clinical trials of B-Raf and/or MEK inhibitors in different grade BRAF-mutated gliomas." (PMID 34804975, 2021). "In our cohort of 13 patients (n = 5 BRAF V600E, n = 4 BRAF WT, n = 4 healthy controls) we characterize the mutant allele frequency in all tumor tissues as well as the plasma samples from patients with confirmed BRAFV600E gliomas." (PMID 33799709, 2021). "The positive clinical response to Dabrafenib in these BRAF V600E adult malignancies has opened doors to several trials of the drug in paediatric gliomas, in which the initial findings demonstrated that Dabrafenib in BRAF V600-relapsed or refractory pLGGs showed an overall response rate of 41%." (PMID 33557011, 2021). "This article reviews critically the use of BRAF V600E and H3K27M mutations as biomarkers and targeted options as well as their associated challenges in translating these biomarkers to clinical applications for paediatric gliomas." (PMID 33557011, 2021). "In addition, the diagnostic tools and the potential of liquid biopsy in the detection of BRAF V600E and H3K27M mutations for the diagnosis of paediatric gliomas are discussed intensively." (PMID 33557011, 2021). "The choice of molecular inhibitor, e.g., BRAF, MEK or FGFR depends on the underlying biology, and so biopsy is essential prior to commencing such specific agents in non-NF1 associated pediatric low-grade glioma." (PMID 33532921, 2021). "Similarly, an ongoing clinical trial evaluating safety and efficacy of the MEK inhibitor binimetinib in children with BRAF-activated gliomas or other solid tumours is providing initial promising results." (PMID 34360713, 2021). "The VE-BASKET trial enrolled 24 patients with BRAF V600-mutant gliomas, including 11 recurrent high-grade gliomas (six GBM and five anaplastic astrocytoma); for these patients, the median PFS was 5.3 months (95% CI, 1.8–12.9), the median OS was 11.9 months (95% CI, 8.3–40.1) and the ORR was 9.1%." (PMID 33375286, 2020). "Using cBioPortal, we retrieved studies of both mutations and copy number variations of the BRAF gene in CNS/brain tumors and investigated data from 69 nonredundant glioma patients." (PMID 33489866, 2020). "The BRAF protein is involved in the mitogen-activated protein-kinase (MAPK) signaling pathway (B-Raf/Mek/Erk proteins) and V600E is the most frequent mutation in the BRAF gene described in gliomas, including pediatric (20%) and adult GBM (6%)." (PMID 33375286, 2020).
glioma (continued). "Because of the negative outcome of high-grade glioma, BRAF mutations have gained considerable interest in the possible benefit of the MAPK pathway inhibitors for glioma treatment." (PMID 33489866, 2020). "However, responses in patients with other glioma subtypes have been observed with the use of second- and third-generation BRAF inhibitors, alone or in combination with MEK inhibitors." (PMID 33396284, 2020). "In addition to p.V600E, rare cases of BRAF p.V600D and BRAF p.V504_R506dup have been described in desmoplastic infantile astrocytomas/gliomas and pilocytic astrocytoma, respectively." (PMID 32164789, 2020). "Other works suggested that gliomas could be more responsive to the concurrent use of BRAF and MEK inhibitors dabrafenib and trametinib." (PMID 33375286, 2020). "The BRAF V600E mutation (in addition to other BRAF alterations) is also found more frequently in other glioma subtypes, including pediatric diffuse gliomas and non-infiltrating tumors such as pilocytic astrocytoma and ganglioglioma." (PMID 32640746, 2020). "Furthermore, a glioma mouse model obtained by transferring the activated forms of BRAF V600E, KRAS and AKT to neural progenitor cells in Ink4a/Arflox/lox mice has been reported." (PMID 31345255, 2019). "Recent studies, however, indicate that additional factors such as loss of CDKN2A or telomerase re-activation may significantly influence the clinical outcome of glioma patients with oncogenic BRAF, suggesting a biological heterogeneity within this subgroup." (PMID 31391125, 2019). "Induction of BRAF V600E alone was not tumorigenic; Ink4a/Arf loss in combination produced well-demarcated gliomas showing evidence of growth into the subarachnoid space, recapitulating the characteristics of epithelioid GBM." (PMID 31345255, 2019). "While adult glioma is driven by oncogenic mutations in IDH1/2, serine/threonine-protein kinase B-raf (BRAF) or fibroblast growth factor receptor (FGFR), paediatric cases of DIPG are characterised by mutations in histone proteins as well as developmental signalling proteins." (PMID 31551357, 2019). "In addition, increasing pediatric data is emerging for BRAF and MEK inhibitors in the treatment of surgically inaccessible gliomas that express BRAF V600E mutations, with an acceptable side effect profile in this age group." (PMID 30069716, 2019). "Additionally, first results of clinical application in BRAFV600E-positive glioma indicate that also a proportion of these tumors exhibit intrinsic BRAF-inhibitor resistance." (PMID 31391125, 2019). "BRAF alterations can be found in several tumors of the central nervous system." (PMID 31181803, 2019). "High expression level of circ-BRAF is an independent marker for good prognosis in glioma patients." (PMID 30064463, 2018). "Each molecularly defined diagnostic group, i.e. IDH-mutant astrocytomas or oligodendrogliomas, histone-mutant gliomas, BRAF-mutant gliomas and ependymomas will be discussed separately with an emphasis on the specific molecular alterations in each group and their clinical relevance." (PMID 29098416, 2018). "BRAF activating rearrangements were reported to be present in 70% of the pilocytic astrocytomas, in 15% of other low-grade gliomas, and have only been punctually observed in high-grade gliomas." (PMID 30558563, 2018). "Incidence and interplay of the presence of BRAF V600E mutation and 9p21 region deletion was evaluated in a series of 78 LGG and 22 HGG aiming to determine the role of these two alterations in recurrence and gliomas’ malignant transformation." (PMID 30558563, 2018).